SPP1 (secreted phosphoprotein 1)
Diseases named in the same sentence as SPP1 in open-access papers (continued):
Sharing a sentence is not in itself a finding about the gene and the disease.
colorectal cancer (continued). "In this study, we conducted differential gene expression analysis on three GEO datasets and confirmed SPP1, MMP1, CXCL8, CXCL1, TIMP1, MMP3, and CXCL10 as core regulatory genes in colorectal cancer through a protein-protein interaction network." (PMID 37842645, 2023). "In colorectal cancer (CRC), tumor-specific FAP+ fibroblasts and SPP1+ macrophages colocalized in the tumor area, which were proved contributed to desmoplastic TME." (PMID 36313703, 2022). "SPP1 is over-expressed in a variety of malignant neoplasms, consisting of medullary thyroid cancer, HCC, as well as colorectal cancer, and is involved in metastasis and tumorigenesis." (PMID 36059672, 2022). "Here, we identify the presence of diversified tumor microenvironment landscape in colorectal cancer, in which FAP+ fibroblasts and SPP1+ macrophages are enriched in the tumor tissue." (PMID 35365629, 2022). "In colorectal cancer (CRC), SPP1 was highly upregulated and increased CRC metastasis by promoting epithelial-mesenchymal transition (EMT)." (PMID 36303551, 2022). "The existence of SPP1+ TAMs and FLOR2+ TAMs in human colorectal cancers were also validated using immunofluorescent staining." (PMID 36172359, 2022). "Spp1+ macrophages engage in the remodeling of ECM via TGFB1 signal in fibroblasts, thereby elevating the expression of MMPs and the deposition of collagens in colorectal cancer." (PMID 40664639, 2025). "SMAD4, ID1, SPP1 and PAK3 mRNA expression also appeared to have prognostic implications for colorectal cancer using the TCGA cohorts, and with further evaluation required in extended human cohorts, are candidate functional readouts associated with disruption of the TGF-β-BMP-SMAD4 pathway." (PMID 40348815, 2025). "In colorectal cancer, tumor-specific FAP-positive fibroblasts and SPP1-positive macrophages are closely localized, which may contribute to poor patient survival." (PMID 37806992, 2023). "Using public scRNA-seq data of patients with colorectal cancer, we observed a significant negative correlation between the proportions of SPP1+ TAMs and CD74+ TAMs, further supporting the distinct evolutionary paths of inflammatory (i.e., SPP1+) and antigen-presenting (i.e., CD74+) TAMs." (PMID 40312419, 2025).
melanoma (131 papers, 2004 to 2026). A malignant, usually aggressive tumor composed of atypical, neoplastic melanocytes. "Further survival analysis indicated that high levels of SPP1 + SIRPα + macrophages were associated with a favorable prognosis in melanoma patients treated with immunotherapy." (PMID 39696410, 2024). "Many studies have reported that OPN (encoded by SPP1) is related to activation of the NF-kappa B signaling pathway in several types of tumors, such as melanoma and renal cell carcinoma." (PMID 39726047, 2024). "The overexpression of SPP1 is associated with a poor prognosis of melanoma, and the inhibition of its expression suppresses the proliferation, migration, and invasion of melanoma cells." (PMID 38731915, 2024). "In summary, overexpression of POSTN in melanoma led to a high number of intratumoral SPP1+ macrophages, which was associated with a significantly reduced response to targeted therapy." (PMID 38942020, 2024). "SPP1 enhances tumor development and its overexpression is associated with poor prognostic outcomes for melanoma, while its silencing suppresses melanoma cell proliferation, migration, as well as invasion." (PMID 35155426, 2022). "The SPP1 mutation frequency was the primary alteration in uterine tumors, melanoma, stomach tumors, cervical tumors, lung squamous cell carcinoma, colorectal tumors, lung adenocarcinoma, GBM, HNSC, ccRCC, and LGG." (PMID 35067176, 2022). "Mutation and amplification were observed to be the main alteration frequency with mutation types of SPP1, especially in uterine cancer and melanoma." (PMID 35067176, 2022). "We previously identified SPP1 as a melanoma driver and found a strong association between SPP1 overexpression and poor prognosis." (PMID 35184394, 2022). "Consistent with the in vitro data, SPP1 knockdown in A375 cells caused significant growth delay in xenografted melanoma tumors." (PMID 33052224, 2020). "There was a significant association between elevated SPP1 expression and increasing Breslow thickness (P = 0.002) and unfavorable survival of melanoma patients." (PMID 33052224, 2020). "SPP1 overexpression was associated with poor melanoma prognosis, and silencing SPP1 suppressed melanoma cell proliferation, migration, and invasion." (PMID 33052224, 2020). "SPP1 gene expression was reported to be associated with melanoma progression in whole-genome gene expression profiling, and was later confirmed in immunohistochemical studies." (PMID 23934016, 2013). "Gene expression studies examining primary melanomas have shown that increased expression of osteopontin (SPP1) is associated with poor prognosis." (PMID 23934016, 2013). "Moreover, Ki67 IHC staining and TUNEL assay for the excised tumours indicated a significant increase in cell proliferation and decrease in apoptosis when SPP1 was overexpressed in EEF2K‐deficient melanoma cells." (PMID 35184394, 2022). "Given that EEF2K positively regulates both SPP1 and p‐STAT3 and SPP1 is positively associated with p‐STAT3 in melanoma, we sought to verify whether EEF2K regulates SPP1 in a STAT3‐dependent manner." (PMID 35184394, 2022). "Similarly, the SPP1 (secreted phosphoprotein 1 )gene product, OPN(osteopontin), was observed in bone metastases; it was also reported that reduced expression of SPP1 in melanoma cells is associated with a lower incidence of bone metastases." (PMID 32204402, 2020). "Specifically, pro-inflammatory CXCL9+CXCL10+ TAMs are enriched in SCC, while tissue-remodelling SPP1+ TAMs are predominant in melanoma." (PMID 41636115, 2026). "Immunofluorescence staining confirmed that SPP1+ macrophage accumulation correlates with advanced stage, metastasis and poor prognosis in the melanoma cohort." (PMID 41636115, 2026). "Further analyses using nomograms in the KIM cohort and the melanoma cohort confirmed the significant role of the “Macro_SPP1-Macro_C1QC-CD8_Tex_C1” triad in immune resistance." (PMID 40740771, 2025).
melanoma (continued). "It has been reported that knockdown of SSP1 in melanoma cells results in significantly reduced tumor growth, and in a B16 mouse melanoma model, SPP1 blockade suppressed melanoma metastasis." (PMID 39819494, 2025). "Inhibition of NF-κB2 leads to decreased SPP1 expression, thereby suppressing melanoma growth and progression." (PMID 41305005, 2025). "Elevated SPP1 expression has been reported in various cancers, including gastric, lung, pancreatic, colorectal, and cervical cancer, as well as in melanomas." (PMID 40362553, 2025). "Spp1 is highly expressed in human melanoma and plays an important role in proliferation, invasion, and metastasis of cancer cells." (PMID 38802348, 2024). "SPP1 is a many-cancer oncogene, including melanoma, potentially promoting proliferation, migration, and invasion and inhibiting apoptosis." (PMID 38732371, 2024). "TREM2+ TAMs from ESCC exhibited a consistent expression pattern and identical signature genes (TREM2, SPP1, APOE, C1QC, C1QB, and C1QA) with melanoma cells, suggesting that TREM2+ TAMs were associated with immunotherapy resistance in ESCC." (PMID 37187751, 2023). "Taken together, these results suggested that EEF2K promotes melanoma progression through the STAT3/SPP1 pathway." (PMID 35184394, 2022). "Taken together, these results supported the notion that SPP1 contributes to EEF2K‐mediated melanoma progression." (PMID 35184394, 2022). "In conclusion, our study demonstrated that EEF2K plays an oncogenic role in melanoma progression via the p‐STAT3/SPP1 axis." (PMID 35184394, 2022). "We previously showed that SPP1 was highly expressed in melanoma, and SPP1 silencing inhibited melanoma cell proliferation, migration and invasion." (PMID 35184394, 2022). "We further demonstrated that bromodomain and extra‐terminal domain (BET) inhibitors impeded melanoma progression through an SPP1‐dependent pathway." (PMID 35184394, 2022). "Mechanistically, we demonstrated that EEF2K upregulates the phosphorylation of STAT3 (p‐STAT3) at Tyr705, which binds to the promoter region of SPP1 and enhances its transcription, thus facilitating melanoma progression." (PMID 35184394, 2022). "Previous research on melanoma showed that SPP1 is a pro-tumoral driver and prognostic factor in melanoma, with bromodomain and extra-terminal domain (BET) inhibitor being a therapeutic agent targeting this protein." (PMID 36148946, 2022). "Based on the identified peak, we designed primers for ChIP‐qPCR analysis, aiming to validate that STAT3 binds to the SPP1 promoter in SK‐MEL‐28 melanoma cells." (PMID 35184394, 2022). "We previously reported that BET inhibitors repressed melanoma progression through the nuclear factor kappa B subunit 2 (NFKB2)/SPP1 pathway." (PMID 35184394, 2022). "As expected, the SPP1 expression was further decreased in melanoma cells after JQ‐1/NHWD‐870 and cytarabine treatment, compared with cytarabine or BET inhibitor treatment alone." (PMID 35184394, 2022). "After silencing STAT3 with siRNA, as indicated by a decrease in STAT3 and p‐STAT3, SPP1 was significantly decreased even in EEF2K‐overexpressing melanoma cells." (PMID 35184394, 2022). "BET inhibitors have been reported to suppress SPP1 expression and here, we further validated the previous findings in melanoma." (PMID 35184394, 2022). "Consistently, based on TCGA datasets, STAT3 was positively correlated with SPP1 in multiple types of cancer, including melanoma." (PMID 35184394, 2022). "Studies have previously shown that stromal SPP1 promotes cancer cell survival and enhances invasion behavior in glioma, prostate cancer, and melanoma, suggesting a direct effect of SPP1 on tumor cells." (PMID 34676217, 2021). "Logistic regression revealed that the key genes responsible for these results were CXCL9 and SPP1 for melanoma and IL6 and CXCL13 for LSCC." (PMID 32383556, 2020). "Next, we used a xenograft model in NSG mice to examine the effect of SPP1 knockdown on melanoma cell growth in vivo." (PMID 33052224, 2020).
melanoma (continued). "In summary, SPP1 expression was positively correlated with melanoma progression, and overexpression of SPP1 predicted poor prognosis in melanoma patients." (PMID 33052224, 2020). "Given that SPP1 was overexpressed in metastatic melanoma, wound healing and Transwell assays were performed to evaluate the role of SPP1 in mediating melanoma migration and invasion, respectively." (PMID 33052224, 2020). "It is known that high levels of MITF, APOE, and SPP1 mark different aspects of melanoma progression, i.e., melanocyte differentiation, angiogenesis, and inflammation, respectively." (PMID 33202765, 2020). "In this study, we found that SPP1 was highly expressed in human melanoma and enhanced cell proliferation, migration, and invasion." (PMID 33052224, 2020). "We found that small interfering RNA-mediated down-regulation of NFKB2 impaired the proliferation, migration and invasion abilities, which mimicked the phenotype of BET inhibitor treatment and SPP1 silencing in melanoma." (PMID 33052224, 2020). "Our study mined multiple gene expression profiles from normal skin, primary and metastatic melanoma, and identified secreted phosphoprotein 1 (SPP1) as a potential melanoma driver." (PMID 33052224, 2020). "Here we found that NHWD-870 directly inhibited melanoma proliferation, migration, and invasion in an SPP1-dependent manner." (PMID 33052224, 2020). "The serum SPP1 concentration was higher in metastatic melanoma patients than healthy individuals, primary melanoma patients, and those who were disease-free for at least five years after treatment." (PMID 33052224, 2020). "To verify SPP1's role in mediating MMP2 expression in melanoma, we knocked down SPP1 in A375 or SK-MEL-28 melanoma cells and found decreased MMP2 expression." (PMID 33052224, 2020). "Silencing of NFKB2 resembled the phenotype of BET inhibitors treatment and SPP1 silencing in melanoma." (PMID 33052224, 2020). "We further confirmed that SPP1 acted as a tumorigenic gene and promoted melanoma cell proliferation, migration, and invasion." (PMID 33052224, 2020). "SPP1 was highly expressed in melanoma cell lines and in patient-derived melanoma short-term cultures." (PMID 33052224, 2020). "Our data demonstrated up-regulated SPP1 expression in melanoma tissues compared with adjacent tissues." (PMID 33052224, 2020). "Real-time PCR (RT-PCR) and Western blotting were employed to quantify SPP1 expression in melanoma cells and tissues." (PMID 33052224, 2020). "Of note, homozygous C alleles in rs11730582 were previously demonstrated to drive significantly more abundant expression of SPP1 mRNA in melanoma cells compared to either heterozygous CT or homozygous TT genotypes." (PMID 32849198, 2020). "Overexpression of SPP1 partially reversed MMP2 expression in melanoma cells after BET inhibitor treatment." (PMID 33052224, 2020). "IHC staining showed higher intensities of SPP1 in melanoma tissues than in tumor-adjacent normal tissues." (PMID 33052224, 2020). "To assess the SPP1 function in melanoma, we stably suppressed SPP1 expression using two independent shRNAs in A375 and SK-MEL-28 melanoma cell lines." (PMID 33052224, 2020). "As observed for PTH‐differentiated osteoblast cells, incubation of hFOB 1.19 precursors with melanoma‐CM was sufficient to increase expression of the osteoblast markers PTHrP and SPP1." (PMID 31323160, 2020). "Next, we analyzed SPP1 expression in different cell lines and found that it was highly expressed in melanoma cell lines compared to HEK-293T and HaCaT cells." (PMID 33052224, 2020). "The evidence is being constantly expanded on the role of SPP1 as a molecular prognostic biomarker in melanoma." (PMID 20805891, 2010). "Several other melanoma cell lines exhibited minimal SPP1 protein expression (MCC12F, 66C, 80a and 89), with comparable findings noted between melanoma cell lysates and conditioned cell media." (PMID 18442402, 2008).
melanoma (continued). "Osteopontin (SPP1) protein expression was examined from melanoma cell lysates and conditioned cell free media derived from 2 primary and 6 MM daughter cell lines." (PMID 18442402, 2008). "SPP-1 expression has been strongly correlated with invasive melanoma but found highly expressed in only 72% of invasive primary melanomas." (PMID 18442402, 2008). "Our data shows that SPP-1 gene expression increases when thin primary melanomas thicken and that SPP-1 is expressed in daughter melanoma cell lines and secreted as a soluble protein." (PMID 18442402, 2008). "Abundant secretion of SPP1 acts as a marker for breast and prostrate cancer, osteosarcoma, glioblastoma, squamous cell carcinoma and melanoma." (PMID 17989776, 2007). "Functional assays confirm that melanoma cells could drive M2 polarisation and SPP1 upregulation in macrophages." (PMID 41636115, 2026). "Notably, VEGFA and SPP1 were significant prognosticators both in primary and metastatic tumors, underscoring their broader role in melanoma progression." (PMID 40943183, 2025). "Eleven genes—including TNFRSF21 and SPP1—were markedly upregulated in tumors, suggesting active angiogenic signaling that may drive melanoma progression and metastasis." (PMID 40943183, 2025). "Similarly, another study identified secreted phosphoprotein 1 (SPP1) as a driver of melanoma that can be regulated by bromodomain and extra-terminal domain (BET) inhibitors, which target the noncanonical NF-κB/SPP1 pathway through inhibition of NF-κB2." (PMID 41305005, 2025). "We next searched KEGG pathways and GO terms associated with highly expressed genes in subcluster “Spp1 + ”, which revealed that subcluster “Spp1 + ” was distinguished by upregulation of genes involved in the melanocyte differentiation and melanoma, including an oncogenic transcription factor Mitf." (PMID 38802348, 2024). "In addition, BRD4 promotes the progression of melanoma by regulating the expression of secreted phosphoprotein 1 (SPP1) through the nuclear factor-kappa B2 (NF-κB2) pathway." (PMID 38229152, 2024). "Bromodomain and extra-terminal domain (BET) inhibitors of SPP1 could be beneficial in melanoma therapy by inhibiting cell proliferation, migration, and invasion in an SPP1-dependent manner." (PMID 38732371, 2024). "In addition, some scholars have demonstrated that inhibition of SPP1 expression can inhibit the progression of melanoma." (PMID 36688087, 2023). "In melanoma patients, SPP1 expression was positively correlated with melanoma progression, and higher SPP1 expression indicated a worse prognosis, whereas silencing SPP1 suppressed melanoma cell proliferation, and migration." (PMID 37097499, 2023). "Here, we identified that EEF2K/p‐STAT3/SPP1 may be a novel oncogenic pathway in melanoma progression and could be a potential target for a novel combinational therapy for melanoma." (PMID 35184394, 2022). "Overexpression of SPP1 is related to a poor prognosis of melanoma." (PMID 36349315, 2022). "In the tumour microenvironment, SPP1 could also activate macrophages, induce angiogenesis and promote melanoma growth." (PMID 35184394, 2022). "We validated that EEF2K silencing could enhance the inhibitory effects of BET inhibitors on melanoma, probably by further downregulating SPP1 expression." (PMID 35184394, 2022). "In this study, we found that EEF2K might play a role in the regulation of melanoma progression through the p‐STAT3/SPP1 pathway." (PMID 35184394, 2022). "Based on these results, we speculated that SPP1 functions as an effector of EEF2K in the context of melanoma progression." (PMID 35184394, 2022). "Among these genes, SPP1 caught our attention, not only because it was ranked in the top 10 and was downregulated most significantly based on the real‐time PCR results, but also it was identified as a crucial melanoma driver in our previous study." (PMID 35184394, 2022). "Silencing SPP1 inhibits melanoma cells' migration, invasion, and proliferation." (PMID 36349315, 2022).